CHI3L1 (chitinase 3 like 1)
Diseases named in the same sentence as CHI3L1 in open-access papers (continued):
Sharing a sentence is not in itself a finding about the gene and the disease.
cervical cancer (10 papers, 2010 to 2024). A primary or metastatic malignant neoplasm involving the cervix. "CHI3L1 (known also as YKL-40) was associated with angiogenesis and bad prognosis in tumors such as breast, lung, and cervical cancers." (PMID 37046579, 2023). "Cervical cancer patients with CHI3L1 risk haplotypes tended to have poor survival event (logistic regression model; p = 0.078; OR:2.99, 95% CI: 0.89–10.08)." (PMID 25203433, 2014). "The SNP frequencies or haplotypes of CHI3L1 were further associated with clinicopathologic variables of cervical cancer, cancer recurrence, and patient survival." (PMID 25203433, 2014). "However, cervical cancer patients with the CHI3L1 risk haplotypes AACC or AACT had significant associations with clinical stage and vaginal invasion, while the association with tumor size was marginal." (PMID 25203433, 2014). "This study demonstrated significant associations of CHI3L1 SNPs and haplotypes with the development of pre-cancerous lesions and invasive cancer of the uterine cervix, and revealed that CHI3L1 haplotypes were related to the prognosis of cervical cancer patients." (PMID 25203433, 2014). "Studies have demonstrated the involvement of CHI3L1 in tumor angiogenesis and the formation of angiogenic mimicry in cervical cancer." (PMID 35761838, 2022). "The cervical cancer patients with the CHI3L1 haplotypes AACC or AACT had poor clinicopathologic characteristics and poor recurrence and survival events." (PMID 25203433, 2014). "Cervical cancer patients with the CHI3L1 haplotypes AACC or AACT had poor clinicopathologic characteristics and a poor prognosis." (PMID 25203433, 2014). "CHI3L1 is a potential therapeutic target in the context of cervical cancer." (PMID 35761838, 2022). "Ngernyuang et al30 revealed that CHI3L1 plays a crucial role in Vasculogenic mimicry, which may contribute to tumor invasion of cervical cancer." (PMID 31536166, 2020). "Chitinases and chi-lectins could play a detrimental role in human cancer development, especially CHI3L1 (YKL-40) which has been associated with increased tumor angiogenesis and bad prognosis in many human neoplasms such as breast, lung, and cervical cancers." (PMID 26881065, 2016). "Because CHI3L1 SNPs influence YKL-40 expression, they may subsequently influence the development of diseases such as cervical cancer." (PMID 25203433, 2014). "In the cervical cancer patients with SCC, CHI3L1 risk haplotypes increased the risk of recurrence event (p = 0.011; OR: 7.50, 95% CI: 1.60–35.16) and tended to increase the risk of poor survival event (p = 0.051; OR: 4.36, 95% CI: 0.99–19.14), in logistic regression model." (PMID 25203433, 2014). "CHI3L1 may be involved in the progression of cervical cancer." (PMID 35761838, 2022). "Thus, CHI3L1 haplotypes may be used for further correlation with the development and clinicopathologic variables of cervical cancer and patient prognosis." (PMID 25203433, 2014). "YKL-40, also known as CHI3L1 or human cartilage glycoprotein-39, was shown to be a potential biomarker in the detection and management of cervical cancer." (PMID 24281117, 2010). "The administration of CHI3L1 has been shown to promote endothelial cell migration and tube formation in vitro but fails to protect cervical cancer cells against apoptosis induced by γ-irradiation." (PMID 28143526, 2017). "To date, no study has correlated CHI3L1 SNPs with cervical cancer in Taiwanese women." (PMID 25203433, 2014).
heart failure (10 papers, 2012 to 2025). Inability of the heart to pump blood at an adequate rate to meet tissue metabolic requirements. "Also, associative studies in patients show that the level of CHI3L1 in circulation inversely correlates with the recovery of the ventricular function after MI; however, the causative role of CHI3L1 in the pathophysiology of heart failure had been unknown." (PMID 40013912, 2025). "In the current study, we established the role of CHI3L1 in the pathogenesis of MI‐induced heart failure." (PMID 40013912, 2025). "Given that CHI3L1 is elevated in patients with MI, and the plasma level correlates with adverse clinical outcomes of heart failure, we determined if and in what region CHI3L1 may be upregulated post‐MI." (PMID 40013912, 2025). "Hence, these findings indicate that CHI3L1 is not only a reliable biomarker and predictor of heart failure but also contributes to ventricular remodeling and dysfunction." (PMID 40013912, 2025). "Although there is strong evidence that CHI3L1 is a reliable biomarker of inflammation, tissue remodeling, and cardiovascular disease, whether CHI3L1 contributes to the progression of heart failure remains untested." (PMID 40013912, 2025). "In this study, it was observed that CHI3L1 expression in POAF (+) patients was lower compared to POAF (-) patients, suggesting that decreased CHI3L1 expression may elevate the risk of heart failure in patients." (PMID 39009943, 2024). "CHI3L1 is a glycoprotein and a member of mammalian chitinase‐like proteins that are associated with diseases characterized by inflammation, increased extracellular remodeling, and ongoing fibrosis; however, the exact function of CHI3L1 in heart failure is unknown." (PMID 40013912, 2025). "Therefore, further exploration is needed to determine whether CHI3L1 mediates the occurrence of POAF, thereby contributing to an increased risk of heart failure in patients." (PMID 39009943, 2024). "Among them was CHI3L1, and notably, it exhibited a negative correlation with heart failure." (PMID 39009943, 2024).
metastatic disease (10 papers, 2009 to 2025). "High CHI3L1 immune reactivity is associated with poor prognosis in endometrial cancer patients, and CHI3L1 also plays a role in angiogenesis and primary and metastatic tumors around tumor blood vessels." (PMID 38003338, 2023).
atrial fibrillation (9 papers, 2009 to 2024). A disorder characterized by an electrocardiographic finding of a supraventricular arrhythmia characterized by the replacement of consistent P waves by rapid oscillations or fibrillatory waves that vary in size, shape and timing and are accompanied by an irregular ventricular response. "CHI3L1, also known as YKL-40, is a glycoprotein produced by lipid-laden macrophages in the vessel wall and is expressed in epicardial adipose tissue among individuals with atrial fibrillation." (PMID 37400771, 2023).
bipolar disorder (9 papers, 2017 to 2024). A disorder of the brain that causes unusual shifts in mood, energy, activity levels and the ability to carry out day-to-day tasks. "A recent study suggested a weak but positive correlation between serum Chi3l1 levels and cognitive functions in patients with bipolar disorder." (PMID 39769202, 2024). "In patients with bipolar disorder (BD), a reduction in BD-related brain subregion volume is related to increased plasma levels of Chi3l1, whereas macrophages and macrophage-like cells may be involved in brain volume reduction." (PMID 39769202, 2024).
metastatic cancer (9 papers, 2011 to 2021). A carcinoma which has spread from the original site of growth to another anatomic site. "Chitinase-3 like-protein-1 (CHI3L1) has been found to be overexpressed in many cancers and increased CHI3L1 level in serum seems to correlate with a poor prognosis in patients with metastatic cancer." (PMID 34612767, 2021). "These authors also described that the CHI3L1 has a potential to be a therapeutic target for metastatic cancer." (PMID 29609579, 2018). "Interestingly, CHI3L1 has been reported to be overexpressed in many cancers and increased CHI3L1 level in serum seems to correlate with a poor prognosis in patients with metastatic cancer." (PMID 34612767, 2021). "In this context, CHI3L1 has the potential to be a therapeutic target for metastatic cancer." (PMID 28143526, 2017). "Elevated serum CHI3L1 levels in patients with metastatic cancers, including SCLC, are associated with poor prognosis, although SCLC cell lines display no or very limited CHI3L1 expression." (PMID 26425658, 2015).
small cell lung carcinoma (9 papers, 2010 to 2024). Small cell lung cancer (SCLC) is a highly aggressive malignant neoplasm, accounting for 10-15% of lung cancer cases, characterized byrapid growth, and early metastasis. "In addition, the text-mining score of CHI3L1 and small cell lung carcinoma was 0.653." (PMID 38177294, 2024).
allergic rhinitis (8 papers, 2016 to 2025). Inflammation of the nasal mucous membranes caused by an IgE-mediated response to external allergens. "Moreover, increased expression of YKL-40 and CHI3L1 have been linked to pathogenesis of allergic rhinitis, atopic dermatitis and food allergy." (PMID 37575256, 2023). "Published human studies show that expression of the CHI3L1 gene and YKL-40 protein (the protein encoded by CHI3L1) is associated with food allergy, allergic rhinitis, and atopic dermatitis." (PMID 41012147, 2025).
breast tumor (8 papers, 2012 to 2026). "Evaluation of the role of this protein in tumor promotion via cancer associated fibroblasts (CAF) suggests that CHI3L1 is upregulated in the stroma of breast tumors, as well as in fibroblasts associated with metastases, particularly in the lung." (PMID 36497242, 2022). "Previous studies have demonstrated that CHI3L1 expression is significantly upregulated in the lungs of mice bearing breast tumors." (PMID 40260255, 2025). "Notably, CHI3L1 expression is elevated in metastatic patient samples when compared with the matched primary breast tumor." (PMID 41632530, 2026). "By studying the role of CHI3L1 in the ‘pre-metastatic’ lungs of breast tumor-bearing mice, it was found that overexpression of CHI3L1 induced the production of vascular growth factors CCL2, CXCL2, and MMP-9 by normal mouse alveolar and interstitial macrophages." (PMID 38003338, 2023). "Moreover, a few genes involved in modulation of the extracellular matrix (ADAMTS4, MMP1, MMP3, and angiogenesis (MFAP5, SFRP2, SRPK1, VEGF, and CHI3L1) were found to be expressed at higher levels in the primary breast tumors compared with the bone metastases." (PMID 23174366, 2012).
delirium (8 papers, 2018 to 2026). A disorder characterized by confusion; inattentiveness; disorientation; illusions; hallucinations; agitation; and in some instances autonomic nervous system overactivity. "We also used the high-throughput, aptamer-based SomaScan proteomics platform to identify high preoperative (PREOP) chitinase-3-like-protein-1 (CHI3L1/YKL-40) and high postoperative day 2 (POD2) IL-6 as risk and disease markers of postoperative delirium." (PMID 39199312, 2024). "Five proteins (CHI3L1, IL6, SFRP2, PMP2, and RTN4R) differed in serum in patients with postoperative delirium compared to baseline with corrected p < 0.01 and 11 at p < 0.05." (PMID 30367354, 2018). "In peripheral blood of surgical patients, our prior work has demonstrated that delirium is characterized by higher preoperative levels of the inflammatory markers C-reactive protein (CRP) and chitinase 3-like protein-1 (CHI3L1/YKL-40), as well as a postoperative hyperactive inflammatory response." (PMID 37759795, 2023).
endometrial cancer (8 papers, 2015 to 2024). Primary or metastatic malignant neoplasm involving the endometrium (mucous membrane that lines the endometrial cavity). "CHI3L1 is highly expressed in gynecological tumors such as endometrial cancer, cervical cancer, and ovarian cancer." (PMID 38003338, 2023). "Targeting CHI3L1 as a therapeutic target for endometrial cancer is feasible." (PMID 38003338, 2023). "HE4 (human epididymis protein 4), together with other serum biomarkers, such as CA-125, CA724, CA19-9, and YKL-40, also known as chitinase-3-like 1 protein (CHI3L1) and DKK-3, can contribute to the detection and monitoring of endometrial cancer." (PMID 38893147, 2024).
Hepatitis (8 papers, 2011 to 2025). Inflammation of the liver. "Combining CHI3L1 with other parameters may improve the diagnostic performance for hepatitis- and NASH-related fibrosis." (PMID 40821115, 2025). "In this study, using Con A-induced hepatitis, a commonly used experimental model to study immune-mediated liver injury, we identified that CHI3L1 was a key mediator of immunomodulatory function of hUC-MSCs." (PMID 33664231, 2021). "Our previous study revealed an important role of Chi3l1 in promoting intrahepatic coagulation in concanavalin A-induced hepatitis." (PMID 34110284, 2021). "Given the role of Chi3l1 in promoting intrahepatic coagulation in concanavalin A-induced hepatitis, we hypothesized that Chi3l1 might be involved in platelet recruitment to the liver during AILI." (PMID 34110284, 2021). "In hepatitis C, HCV induces and maintains the production of CHI3L1 in liver parenchymal cells by synergistically inducing the TNF-α and ROS-MAPKs pathways through the sustained activation of NF-κB." (PMID 38962736, 2024).
hepatitis C (8 papers, 2014 to 2024). "In hepatitis C‐infected population, Kamal et al23 discovered that CHI3L1 can accurately determine the speed of fibrosis progression, identifying whether the patient is in the stage of rapid fibrosis or stable disease." (PMID 31916309, 2020). "Researchers at Helwan University studied the risk of HCC susceptibility in Egyptian patients with hepatitis C after SVR through DAA treatment and found that the CHI3L1 gene (rs880633) could serve as a strong predictor and risk factor for patients to develop HCC post-SVR." (PMID 38962736, 2024). "The correlation between CHI3L1 and TGF-β mRNA in the liver and serum of patients with hepatitis C demonstrates that serum CHI3L1 and TGF-β originate from the liver and that serum CHI3L1 levels are positively correlated with TGF-β levels." (PMID 39068486, 2024).
liver cirrhosis (8 papers, 2010 to 2024). "The area under the ROC curve value for CHI3L1 to predict liver cirrhosis was 0.939 (95% CI, 0.8974-0.9814), with 95.1% sensitivity and 84.4% specificity at the cutoff point at 141.23 ng/ml." (PMID 33082884, 2020). "CHI3L1 has the potential to allow the identification of early treatment failure for timely switching to an alternative treatment and to allow monitoring of the progression of fibrosis as a hazard factor for liver cirrhosis and HCC." (PMID 33082884, 2020). "To analyze the predictive value of CHI3L1 for liver cirrhosis patients, we generated a ROC curve." (PMID 33082884, 2020). "A research team from Ningbo University examined the serum CHI3L1 expression in patients with CHB, liver cirrhosis, and HCC and investigated the expression characteristics of chronic liver diseases related to hepatitis B in different stages." (PMID 38962736, 2024). "First, we found that serum level of CHI3L1 correlated moderately but significantly with LSM (r = 0.615, P < 0.001) at the baseline, and diagnosed liver cirrhosis at baseline with high accuracy (AUC = 0.939) by ROC analysis." (PMID 33082884, 2020). "In addition, the values of AUCs in discriminating liver cirrhosis was 0.939, which suggested that CHI3L1 can serve as the serum marker to detect fibrosis in a noninvasive way." (PMID 33082884, 2020).
lymph node metastases (8 papers, 2012 to 2025). "Presence of a homozygous mutant allele of CHI3L1 polymorphisms significantly linked to a reduced risk of lymph node metastasis and was correlated with its mRNA levels in oral cancer." (PMID 40256126, 2025). "Patients with oral cancer who possess the homozygous A/A genotype of the CHI3L1 polymorphisms exhibited a notably reduced risk of lymph node metastasis." (PMID 40256126, 2025). "The CHI3L1 polymorphisms, could potentially serve as biomarkers to predict lymph node metastasis in individuals with oral cancer." (PMID 40256126, 2025). "Two recent studies find that overexpression of CHI3L1 protein is related to PTC with lymph node metastases." (PMID 37480002, 2023). "The CHI3L1 protein-positive rate in patients with lymph node metastasis (85.2%, 23/27) was significantly higher than that in patients without lymph node metastasis (64.5%, 49/76)." (PMID 35761838, 2022). "On univariate Kaplan–Meier analysis, FIGO stage, tumor diameter, lymph node metastasis, vascular invasion, CHI3L1, and MVD of CSCC were related to the prognosis of PFS and OS (all P < 0.05); however, CHI3L1 and MVD were not independent prognostic factors." (PMID 35761838, 2022). "In addition, we evaluated the prognostic significance of CHI3L1 expression according to different clinicopathological factors, and found that significant differences were observed in patients with T3-T4, and lymph node metastasis." (PMID 30165890, 2018). "In addition, in the two malignant groups (OIDM and LM), the expression of CHI3L1 in the distant metastasis group was significantly higher than that in the no metastasis group or the lymph node metastasis group (P < 0.05)." (PMID 37480002, 2023).
neuromyelitis optica (8 papers, 2019 to 2026). A rare inflammatory disease of the central nervous system characterized mainly by attacks of uni- or bilateral optic neuritis (ON) and acute myelitis. "Astrocyte-secreted CHI3L1, an inflammatory biomarker and pathogenic mediator, drives neuromyelitis optica demyelination via a specified receptor signaling mechanism." (PMID 41480772, 2026). "Similar to murine Chi3l3 and Chi3l1, their human paralogues CHI3L1 and CHIT1 are highly abundant in the CNS during acute demyelinating diseases, including relapsing-remitting MS (RRMS) and neuromyelitis optica, but not chronic MS37." (PMID 30644388, 2019).
peripheral arterial disease (8 papers, 2012 to 2024). A disorder of the arteries supplying the upper and lower extremity and the visceral organs. "Additionally, increased Chi3l1 levels are independently associated with poor long-term cardiovascular survival in peripheral arterial disease patients." (PMID 39769202, 2024). "The drug pentoxifylline, approved for peripheral arterial diseases and a known inhibitor of CHI3L1, also appeared as a positive control with a score value of -7.1." (PMID 39225813, 2024). "We attempted to elucidate the genetic, clinical and biochemical correlates of circulating YKL-40 level and, by combining it with CHI3L1 gene variants, with the risk and long-term mortality of peripheral artery disease (PAD)." (PMID 25486056, 2014).
prion disease (8 papers, 2017 to 2025). A transmissible disease that is caused by a protein that is able to induce abnormal folding of normal cellular proteins, leading to characteristic spongiform brain changes, which are associated with neuronal loss without an inflammatory response. "Prion disease-associated astrogliosis is also prominent in human prion diseases as shown by the upregulation of GFAP and YKL-40 (or Chitinase-3-like protein 1; CHI3L1)." (PMID 36230910, 2022).
viral infection (8 papers, 2018 to 2022). "Expression of these genes is associated with movement (MMP9, SPP1, ALCAM, and others), viral infection (APOC1, LGALS3, CD63, and others), and recruitment of phagocytes (APOE, CHI3L1, LGALS3, and others)." (PMID 32723919, 2020). "Because our data demonstrate that CHI3L1 is a potent stimulator of ACE2 and SPP, they also provide a mechanism by which CHI3L1-based interventions can be effective therapies in all SC2 variants that utilize ACE2 and SPP to mediate viral infection." (PMID 35735790, 2022).